TGM2 (transglutaminase 2)
Diseases named in the same sentence as TGM2 in open-access papers (continued):
Sharing a sentence is not in itself a finding about the gene and the disease.
celiac disease (continued). "Celiac disease (CD) is an autoimmune gastrointestinal disorder characterized by the presence of anti-transglutaminase 2 (TG2) and anti-gliadin antibodies." (PMID 20300628, 2010). "In celiac disease, autoantibody reactivity to transglutaminase 2 (tTG2) has been shown to closely correlate with the acute phase of the disease." (PMID 19220902, 2009). "In celiac disease gluten, the disease-inducing toxic component in wheat, induces the secretion of autoantibodies which are targeted against transglutaminase 2 (TG2)." (PMID 18312620, 2008). "For example, in celiac disease patients, an inflammatory response to dietary gluten leads to enteropathy, malabsorption, circulating antibodies against gluten and transglutaminase 2, and clinical symptoms such as diarrhea." (PMID 18286171, 2008). "mTG mimics the enzymatic function of human transglutaminase 2 (TG2) and may play a role in the pathogenesis of celiac disease." (PMID 40787731, 2025). "Due to the expanding screening of coeliac disease (CeD), low positive and borderline negative serum transglutaminase 2 antibody (TGA) values are causing increasing confusion in clinical practice." (PMID 40994413, 2025). "Celiac disease (CD) is a systemic autoimmune disorder with T lymphocyte activation to ingested gluten peptides and coupled autoantibody production to the transglutaminase 2 (TG2) autoantigen, leading to the damage of the villous structure in the small intestines." (PMID 39940781, 2025). "Of note, although it was reported that TGM2 activation was associated with the development of cancer, celiac disease and neurodegenerative diseases, no obvious tumors, diarrhea, and cognitive behavioral impairments were found in mice during FSK administration." (PMID 37088726, 2023). "TGM2 is a multifunctional enzyme with transglutaminase crosslinking, G protein signalling, and kinase activities that are postulated to play a role in many disease states, including celiac disease and cancer." (PMID 36765657, 2023). "TGM2 enzymatic activity has been extensively studied, the crystal structure has been resolved, and specific small molecule inhibitors have been successfully translated into clinical trials for the treatment of celiac disease." (PMID 37443286, 2023). "The enzyme transglutaminase 2 (TG2) plays a key role in celiac disease (CeD) pathogenesis." (PMID 37445994, 2023). "In addition, both deamidated gluten peptides (DGP) and the self-protein transglutaminase 2 (TG2) become the targets of the B-cell response in celiac disease." (PMID 34731200, 2021). "Thanks to these characteristics, it has been applied as a potential biosensor for the detection of transglutaminase 2 (TG2), a multifunctional enzyme linked to several pathologies (e.g., cancer, cardiovascular disease, celiac disease, and neurodegenerative diseases)." (PMID 34884467, 2021). "For this reason, IgG and IgA native antigliadin antibodies (AGA) are currently the most sensitive marker for GA when compared to endomysium (EMA) and transglutaminase 2 antibodies (TG2), both of which are specific for the presence of enteropathy (Coeliac Disease-CD)." (PMID 30301184, 2018). "Coeliac disease (CD), an enteropathy caused by cereal gluten ingestion, is characterized by CD4+ T cells recognizing deamidated gluten and by antibodies reactive to gluten or the self-antigen transglutaminase 2 (TG2)." (PMID 24909383, 2014). "In addition, patients with celiac disease typically develop antibodies to gliadin and autoantibodies specific for endogenous enzyme transglutaminase 2 (TG2)." (PMID 23823806, 2013). "The increased expression of transglutaminase 2 found in the enterocytes and basement membrane in active coeliac disease could cross-link with SPRR3 to form a cornified envelope-like barrier." (PMID 18691394, 2008).
celiac disease (continued). "In addition, in patients with celiac disease, an autoimmune gluten-sensitive enteropathy, the deficiency of galactosylation on IgA targeted or non-targeted with transglutaminase 2 (TG2) has also been found in their circulatory system." (PMID 36238099, 2022). "In addition to the reaction of the SARS-CoV-2 antibodies with tight junction proteins, the human monoclonal antibodies made against spike protein and nucleoprotein reacted with transglutaminase-2 (tTG-2), an enzyme in the intestinal mucosa that plays a role in celiac disease." (PMID 33584709, 2020). "Transglutaminase 2 (TG2), an enzyme secreted into the extracellular matrix during inflammation, plays an important role in the pathophysiology of celiac disease by promoting the creation of antigliadin antibodies." (PMID 40184064, 2025). "Transglutaminase 2 (TG2) is an enzyme involved in tissue repair, but in certain diseases, such as celiac disease, it can trigger harmful immune reactions." (PMID 40575215, 2025). "Transglutaminase 2 (TG2) is a GTP-binding, protein-crosslinking enzyme that has been investigated as a therapeutic target for Celiac disease, neurological disorders, and aggressive cancers." (PMID 39134806, 2024). "Heparan sulfate proteoglycans (HSPGs), syndecan-4 (Sdc4) especially, have been suggested as potential partners of transglutaminase-2 (TG2) in kidney and cardiac fibrosis, metastatic cancer, neurodegeneration and coeliac disease." (PMID 30621228, 2019). "Since serum IgA and IgG anti‐tissue transglutaminase 2 (anti‐TG2) titres were over 100 U/ml and HLA typing revealed DR3‐DQ2/DR7‐DQ8 haplotypes, he was diagnosed with coeliac disease (Fig EV1)." (PMID 29567797, 2018). "In addition, MBCs from CD patients exhibited increased usage of IgHV3-48, which was overrepresented in transglutaminase 2 (TG2)-specific PCs and MBCs from patients with celiac disease." (PMID 40160682, 2025). "Non-biopsy diagnosis of celiac disease is possible in children with anti-transglutaminase 2 antibodies (TGA) > 10× the upper limit of normal (ULN) and positive anti-endomysial antibodies (EMA)." (PMID 32911716, 2020). "In people, positive Transglutaminase-2 IgA results have been reported in patients suffering from autoimmune diseases such as type 1 diabetes, autoimmune liver disease, Hashimoto's thyroiditis, psoriatic or rheumatoid arthritis, and heart failure, who do not have celiac disease." (PMID 36937013, 2023). "At the same time, modern sensitive and specific transglutaminase 2 (TG2) antibody based serological tests have made non-invasive case finding and screening of celiac disease considerably easier." (PMID 30081502, 2018).
breast carcinoma (98 papers, 2005 to 2025). "It has multiple functions that are important in cancer biology and several small studies have suggested expression of TGM2 in breast cancers is associated with a poorer prognosis." (PMID 39516660, 2024). "Several studies have reported on the association between TGM2 expression and prognosis in breast cancer with increased expression being associated with a poorer prognosis." (PMID 39516660, 2024). "In breast cancer, expression of TGM2 in tumor stroma is an independent risk factor for breast cancer patients at high risk of recurrence." (PMID 29137349, 2017). "Silencing of TGM2 in MDA-MB-231 has been shown to reverse EMT and lower expression of TGM2 is associated with increased sensitivity to chemotherapeutic agents in breast cancer." (PMID 28235006, 2017). "TGM2–integrin–fibronectin associations have previously been implicated in the cell motility and invasion of breast cancer cells." (PMID 23765377, 2013). "TGM2 has been identified as an important factor in variant types of cancer (such as gastric cancer, ovarian cancer, colorectal cancer, breast cancer, etc.), and importantly its elevated expression level in tumor tissues is commonly linked to worse disease outcomes and poor survival rates." (PMID 39115570, 2024). "As expected, H3Q5dop was also found to accumulate in colorectal and breast cancer cells, which could be attributed to the high expression level of TGM2 in these cells, further highlighting its close association with cancer progression." (PMID 39115570, 2024). "TGM2 is associated with metastatic breast cancers and multi drug resistant tumors." (PMID 21853032, 2011). "Similar cytokine responses have been reported following TGM2 knockdown in colorectal and breast cancer models, indicating that TG modulation broadly influences tumor immune responses." (PMID 41425727, 2025). "In conclusion, TGM2 not only represents a promising therapeutic target but also serves as a potential prognostic marker for breast cancer." (PMID 39544364, 2024). "Downregulation of P-glycoprotein (P-gp) and Transglutaminase 2 (TG2) has been identified as a potential mechanism to sensitize drug-resistant breast cancer cells to chemotherapy." (PMID 37049499, 2023). "Others have shown that transglutaminase 2 (TG2) downregulates miR-205 in breast cancer cells and thereby promotes bone metastasis." (PMID 35158995, 2022). "(b) Distant metastasis-free survival Kaplan-Meier plot for TGM2 expression in all breast cancer subtypes." (PMID 36475545, 2022). "Transglutaminase-2 (TG2) induces EMT in various tumours, and its overexpression in human MCF-7 breast cancer cells (MCF7/TG2-C277S) promotes bone metastasis formation in nude mice." (PMID 33830428, 2021). "miR-205 downregulation by transglutaminase 2 (TG2) enhances breast cancer bone metastasis and invasion." (PMID 33435254, 2021). "As a soluble protein, secreted CLIC3 promotes angiogenesis and invasion of ovarian cancer cells and breast cancer cells both in vivo and in 3D cell culture models by reducing transglutaminase-2." (PMID 32066374, 2020). "To investigate this marker in breast cancer patient samples, first we analyzed the RNA expression of TGM2 in patients with different stages of breast cancer that showed significant increase in tumors compared to adjacent normal or other normal tissues." (PMID 33294017, 2020). "To validate these observations in an additional model of breast cancer metastasis, we deleted TGM2 using a CRISPR-mediated gene editing approach in the highly metastatic 4T1 cells." (PMID 32054828, 2020). "TGM2 is overexpressed in many types of cancer, including pancreatic carcinoma, breast cancer, ovarian carcinoma, and lung cancer." (PMID 32923383, 2020). "For example, EDIL3 is involved in the progression of breast and bladder cancers), while TGM2 mediates chemoresistance of both lymphoma and breast cancer." (PMID 31416147, 2019).
breast carcinoma (continued). "Transglutaminase 2 expression is linked to an increase in CD44+ (and CD24−) subpopulations in breast cancer cells, leading to promotion of stem-like properties and a metastatic phenotype." (PMID 30691081, 2019). "A higher proportion of mammary tumors showed to express transglutaminase 2 in the chemoprevention group, while its upregulated expression is suggestive of an increased aggressiveness of tumors." (PMID 31877708, 2019). "Chloride intracellular channel protein 3 (CLIC3) secreted by breast cancer CAFs induces angiogenesis through an active transglutaminase-2 (TGM2) mediated mechanism." (PMID 30380628, 2018). "Brown reviewed that NF-κB pathway activation upregulates TGM2 level in the breast cancer, and Kiziltas reported that NF-κB pathway activation is the common downstream pathway of TLR4 signal pathway activation in the liver." (PMID 29321784, 2017). "To gain insight into the clinical role of TGM2 we first evaluated its expression in two publicly available gene expression datasets of stromal and tumor cells laser-capture microdissected from breast cancer clinical specimens." (PMID 27600076, 2016). "We have recently demonstrated that detection of any of these EMT-related transcription factors (EMT-TFs) or TGM2 in the peripheral blood of breast cancer patients can serve as a surrogate for circulating tumor cells (CTC) in breast cancer patients." (PMID 26207636, 2015). "From the microarray analysis, we choose TGM2 for further study, because TGM2 has been reported as a prognostic marker for laryngeal cancer or colorectal cancer as well as a chemotherapy-resistance marker for breast cancer and lung cancer." (PMID 25247996, 2014). "In support of this, TGM2 was identified by microarray analysis as one of the genes up-regulated in T47D breast cancer cells after OSM treatment." (PMID 23765377, 2013). "Recent studies have shown that TGM2 promotes drug resistance and invasion by inducing a stem cell-like phenotype in ovarian and breast cancer." (PMID 23865481, 2013). "Increased expression of TGM2 has been observed in many types of cancer, including pancreatic cancer, breast cancer, malignant melanoma, ovarian cancer, lung cancer, and glioblastoma." (PMID 22294552, 2012). "In our quest to determine the significance of elevated tissue transglutaminase 2 (TG2) expression in drug-resistant and metastatic breast cancer cells, we found that stable expression of TG2 in mammary epithelial cells is associated with EMT." (PMID 22225906, 2012). "TGM2 expression can promote cell surface interaction with fibronectin and protect breast cancer cells from apoptosis." (PMID 22458929, 2012). "TGM2 expression was also increased in MCF7 (breast cancer), DU145 (prostate cancer), and A549 (lung cancer) cell lines in response to two other EMT-inducers TNFα and EGF, demonstrating that increased TGM2 expression is consistently associated with the EMT process." (PMID 40777010, 2025). "In conclusion, we have found evidence to support previous publications that have suggested breast cancers that express TGM2 in the stoma are associated a poorer than those that do not express TGM2." (PMID 39516660, 2024). "The aim of this study was to evaluate the role of intra-cellular and extra-cellular TGM2 expression in breast cancer and to determine whether there were any differences by hormone receptor status." (PMID 39516660, 2024). "Tissue compartment and hormone receptor status differences in the effect of TGM2 expression on clinical outcomes of breast cancer may reflect the different functions of TGM2." (PMID 39516660, 2024). "However, TGM2 and TGM2 are up-regulated in breast cancer and TGM2 has been shown to play multiple roles in the biology of breast cancer including cell adhesion, invasion and survival, programmed cell death, cell signalling, and metabolic reprogramming." (PMID 39516660, 2024).
breast carcinoma (continued). "Here, we show that cancer cells of human pancreatic ductal adenocarcinoma (PDA), colorectal cancer, and breast cancer are coated with transglutaminase-2 (TGM2)–dependent covalent CXCL12–keratin-19 (KRT19) heterodimers that are organized as filamentous networks." (PMID 35046049, 2022). "Additionally, breast cancer patients exhibited significantly decreased distant metastasis-free survival with high TGM2 expression compared to low TGM2 expression (Győrffy, 2021)." (PMID 36475545, 2022). "Transglutaminase-2 can facilitate extracellular vesicle-mediated establishment of the metastatic niche, while pyruvate carboxylase enhances the pulmonary tropism of metastasis in breast cancer." (PMID 34123800, 2021). "Moreover, miR-205 is inhibited by the transglutaminase 2 (TG2) in order to induce EMT in breast cancer cell lines; the GTP binding activity of TG2 represses miR-205 expression, thus allowing ZEB1 expression and function in in vitro assays." (PMID 33375067, 2020). "TGM2 modulates chemosensitivity of breast cancer to docetaxel." (PMID 32867128, 2020). "In a nutshell, TGM2 might provide a new target for the diagnosis and treatment of breast cancer, as substantial evidence have shown that down-regulated TGM2 expression can decrease the invasive ability and metastatic potential of breast cancer." (PMID 31877708, 2019). "Hence, the CLIC3/TGM2 pathway promotes angiogenesis in vivo, and breast cancer invasion in 3D culture and in vivo." (PMID 28198360, 2017). "To determine whether rapamycin treatment promotes TGM2 expression in other cancer cell lines, we measured Tgm2 transcript levels in MCF-7 (PTEN-mutant breast cancer) and 786-O (PI3K-mutant renal cancer) cells." (PMID 26872016, 2016). "We previously reported that IL-6 and transglutaminase 2 (TG2) were expressed in more aggressive basal-like breast cancer cells, and TG2 and IL-6 expression gave these cells stem-cell-like phenotypes, increased invasive ability, and increased metastatic potential." (PMID 27609180, 2016). "Unfortunately, no publicly available gene expression datasets of breast cancer stromal samples with associated clinical data were available to test the prognostic value of stromal TGM2 expression." (PMID 27600076, 2016). "In cancer, transglutaminase 2 has been shown to play a major role in development of drug resistance and metastasis in many cancer types, including pancreatic carcinoma, ovarian carcinoma, malignant melanoma, lung carcinoma, glioblastoma, and breast carcinoma." (PMID 24778599, 2014). "Transglutaminase 2 (TG2) expression in cytoplasm and stroma in breast cancer." (PMID 24058567, 2013). "Thus, tumour TGM2 expression is a good candidate as a biomarker of prognosis in breast cancer." (PMID 39516660, 2024). "We have found modest evidence for an association between intra-cellular expression of TGM2 in the tumour cytoplasm and an improved prognosis in early breast cancer with a bigger effect in hormone-receptor-negative disease than in hormone-receptor positive disease." (PMID 39516660, 2024). "The aim of this work was to assess the association between expression of TGM2 in both tumour and stromal compartment in invasive hormone receptor positive and hormone receptor negative female breast cancer in a cohort of 2169 women with early invasive breast cancer." (PMID 39516660, 2024). "Using the TNMplot database, we found that TGM2 expression of breast cancer patients increased from normal tissue to breast tumor tissue to metastatic tissue (Bartha and Győrffy, 2021), indicating that TGM2 expression was correlated with breast cancer metastasis." (PMID 36475545, 2022). "Our data suggest that OSM–OSMR interactions may also be responsible for inducing TGM2 in other cell types, such as breast cancer cells, in which OSM promotes cell motility and metastatic behaviour and TGM2 has been associated with migration, invasion and metastasis 29–33." (PMID 23765377, 2013).
breast carcinoma (continued). "It was found that the extracellular vesicles (EVs) isolated from metastatic breast cancer cells underwent EMT-MET (mesenchymal–epithelial transformation) and that TG2 (Transglutaminase-2) and FN expression was upregulated in the cells." (PMID 36358270, 2022). "We selected transglutaminase-2 (TGM2), which forms isopeptide bonds between glutamines and ε-amino groups of lysines, as the candidate because it is expressed in human PDA, CRC, and breast cancers and is present in lysates of the SKBR3 and Caco2 cell lines." (PMID 35046049, 2022). "Furthermore, TGM2 inhibitor such as cystamine, glucosamine, or KCC009 effectively promote cell death in glioma, breast cancer, or pancreatic cancer." (PMID 25247996, 2014). "Finally, TGM2 did not exhibit statistically significant differences in breast carcinoma, glioblastoma, ovarian cancer, and colon adenocarcinoma." (PMID 38474044, 2024). "(c) Distant metastasis-free survival Kaplan-Meier plot for TGM2 expression in ER, PR, and HER2 negative breast cancer." (PMID 36475545, 2022). "The mRNA levels of TGM2, SASH1, PARP9, STAT1 and ANXA1 were not significantly different between ER+ and ER--breast cancer tissues." (PMID 29416786, 2018).